Y_RNA (Y RNA )
Gene: Miscellaneous RNA gene on chromosome 5 (23,299,155 to 23,299,262, forward strand). Ensembl gene ENSG00000206912.
Homologues: Orthologues: chimpanzee Y_RNA (100% identical), guinea pig Y_RNA (81% identical). Paralogues in human: RNY1 (84% identical), Y_RNA (84% identical), Y_RNA (83% identical), Y_RNA (82% identical), Y_RNA (81% identical), RNY1P11 (81% identical), RNY1P8 (81% identical), Y_RNA (80% identical), RNY1P12 (79% identical), Y_RNA (79% identical), RNY1P5 (78% identical), RNY1P7 (78% identical), and 94 more.